CDH1 (cadherin 1)
Diseases named in the same sentence as CDH1 in open-access papers (continued):
Sharing a sentence is not in itself a finding about the gene and the disease.
gastric cancer (continued). "Given the association between CDH1 mutations and both HLBC and HDGC, a family history of gastric cancer should be considered in screening protocols, even if individual patients have not developed gastric cancer themselves." (PMID 40366456, 2025). "Individuals with CDH1 and a family history of gastric cancer are presumably more likely to have a screening endoscopy at a younger age because of cascade genetic testing." (PMID 39760880, 2025). "The International Gastric Cancer Linkage Consortium (IGCLC) has established clinical criteria for identifying families at risk, emphasizing the importance of genetic testing for CDH1 mutations in individuals with a family history of gastric or LBC." (PMID 40585607, 2025). "Familial clustering studies reveal that germline mutations in CDH1 (E-cadherin) and polymorphisms in IL-1β and TNF-α genes heighten susceptibility to CAG and gastric cancer." (PMID 40612582, 2025). "The most common cancers in CDH1 PV carriers included breast cancer (54.6%), gastric cancer (39.7%), and CRC (9.9%)." (PMID 40323501, 2025). "Among these, gastric cancer and pathways in cancer were the two key pathways associated with CTNNB1 and CDH1." (PMID 40150405, 2025). "Spearman correlation analysis using the GSE2685 gastric cancer dataset revealed that AKR1B1 expression was inversely correlated with CDH1 expression." (PMID 38200154, 2024). "For instance, p16 demonstrates hypermethylation in colorectal cancer, leukemia, and gastric cancer, as well as CDH1, APC, and CDH13 in leukemia." (PMID 39246954, 2024). "The International Gastric Cancer Linkage Consortium (IGCLC), in 1999, defined clinical criteria to select patients for the screening of CDH1 germline variants." (PMID 37686589, 2023). "CDH1 (E-cadherin), a member of the cadherin-catenin complex, is an example in which pathogenic variants can lead to CLP and/or gastric cancer." (PMID 37225711, 2023). "In the family of two patients with gastric cancer, one confirmed DGC, and one patient with lobular breast cancer, CDH1 gene testing was recommended according to the latest International Gastric Cancer Linkage Consortium (IGCLC) consensus guidelines." (PMID 37393258, 2023). "Current gastric surveillance recommendations from the International Gastric Cancer Linkage Consortium (IGCLC) for carriers of a PV in CDH1 or CTNNA1 help inform this decision and are based on family history of DGC121." (PMID 37165697, 2023). "As a result of HRM-analysis of the CDH1 gene locus, we identified only one DNA sample from the blood of a patient with gastric cancer with differences in melting temperature." (PMID 36833207, 2023). "HDGC is associated with PVs in either the CDH1 or CTNNA1 gene and confers the highest risk of DGC amongst all of the known hereditary gastric cancer risk syndromes." (PMID 37165697, 2023). "Therefore, since CDH1 is a Gastric Cancer target gene, we can state that the new variant found in our investigation may have an extremely important role in terms of cell cycle modulation, making it necessary to carry out further investigations to understand its biological impact." (PMID 37763132, 2023). "Diffuse-type and, in particular, the GS molecular subtype of gastric cancer are also enriched for CLDN18-ARHGAP fusions, which seem to be mutually exclusive with RHOA and CDH1 mutations." (PMID 36812376, 2023). "This was performed in a human gastric cancer cell line bearing normal CDH1/E-cadherin expression and function." (PMID 37249750, 2023).
gastric cancer (continued). "To understand the frequency of and explore potential mechanisms which underly E- to P-cadherin switching in gastric cancer, we started by analysing RNA-seq data from 43 gastric cancers to evaluate CDH1 and CDH3 mRNA expression." (PMID 37372088, 2023). "We induced this switch by depleting CDH1 in gastric cancer cells, and, as they started to produce CDH3, this rescued cell-adhesion." (PMID 37372088, 2023). "Despite the high incidences of gastric cancers in East Asian countries compared with Western countries, HDGC harboring CDH1 variants has rarely been reported." (PMID 36719602, 2023). "Our data provide evidence that loss of E-cadherin is able to compromise the normal interactions between the CDH1 to CDH3 gene sequences, allowing the expression of P-cadherin in gastric cancers." (PMID 37372088, 2023). "Knockdown of ARID1A in gastric cancer cell lines led to reduced E-cadherin (CDH1) expression, disruption of the cadherin/catenin complex, epithelial–mesenchymal transition, and enhanced invasive properties of the cells." (PMID 38275587, 2023). "HDGC accounts for 1–3% of all gastric cancers, and the majority of cases of CDH1-related HDGC reported to date have been in Western countries." (PMID 36719602, 2023). "Germline pathogenic variants in the E-cadherin gene CDH1 cause hereditary diffuse gastric cancer (HDGC), which is an autosomal dominant cancer syndrome, accounting for 1–3% of all gastric cancers." (PMID 36719602, 2023). "Eight pediatric patients with gastric carcinoma were enrolled in the STEP registry, among whom two were patients with hereditary CDH1 mutations and another was a patient with Peutz–Jeghers syndrome." (PMID 36612313, 2023). "Conversely, the levels of the tumor suppressors (e.g., DAPK1, TIMP3, GRIN2B, SLC5A8, and CDH1) are low in the gastric tissues of patients with gastric cancer." (PMID 35211104, 2022). "According to the International Gastric Cancer Linkage Consortium (IGCLC), patients who meet the inclusion criteria for HDGC must be tested for CDH1 germline mutations." (PMID 35327954, 2022). "Decreased amounts of both pT606‐Kaiso and CDH1 proteins were frequently observed in human gastric cancer tissues compared to paired normal controls." (PMID 35851744, 2022). "In our study, somatic CDH1 mutations and FGFR2 CNV gains were identified to enrich in the younger gastric cancer patients." (PMID 35498538, 2022). "Given that both AKAP9 and CDH1 are frequently altered in gastric cancer and play a vital role in controlling gastric cancer cell migration, we next examine the correlation between these two functional-relevant events." (PMID 36317124, 2022). "In the largest study to date evaluating CDH1 germline variants, we found significant enrichment of P/LP variants in patients with CSRCC, CRC, breast, and gastric cancer." (PMID 34949788, 2022). "The diffuse subtype which represents a small minority of gastric cancer, is genomically stable and associated with decreased expression of CDH1 (E-cadherin), higher expression of RhoA and prominent mesenchymal features, thus resulting in tumor aggressiveness." (PMID 35203450, 2022). "The results of this study showed that TGFβ1, TGFβ2 and TGFβ3 were positively correlated with EMT, CDH2, VIM and ZEB1 and significantly negatively correlated with CDH1 in multiple gastric cancer datasets." (PMID 36119489, 2022). "Detailed individual and family criteria for CDH1 germline genetic testing have been developed by the International Gastric Cancer Linkage Consortium." (PMID 36246616, 2022).
gastric cancer (continued). "Some of these were supported by evidence in the literature, including BRAF-DUSP4, BRAF-MAPK1, and BRAF-PEA15 in skin, GATA3-ESR1 in breast, and CDH1-CTNNB1 in stomach cancers." (PMID 36517508, 2022). "By applying a threshold of 1.5-fold change (0.58 in log2) to the log2 ratio ITGB1/CDH1, we were able to discriminate two different groups of gastric carcinoma cases." (PMID 34486077, 2022). "The reduction in H3K36me3 promotes the expression of the CDH1 (cadherin 1) isoform with exon 8, acting as a biological marker in gastric cancer occurrence." (PMID 33407694, 2021). "In 1999, the International Gastric Cancer Linkage Consortium (IGCLC) defined the hereditary diffuse gastric cancer (HDGC) syndrome and established clinical criteria for CDH1 genetic screening of individuals and families at risk." (PMID 33809393, 2021). "Patient III.1 of gastric cancer family 1 with a heterozygous deletion of CDH1 exons 8 to 11 was diagnosed with a pituitary adenoma, i.e. a prolactinoma, at age 27 years after having had a gastric carcinoma two years earlier." (PMID 33929593, 2021). "Promoter hypermethylation is considered to be another major mechanism for CDH1 inactivation in the development of various cancers, including gastric cancer." (PMID 34422902, 2021). "To better understand the relationship between the different HDAC classes and CDH1 expression in gastric cancer, we performed hierarchical clustering on gene-expression data from 415 gastric cancers (TCGA and STAD dataset)." (PMID 35008338, 2021). "About 30% of families fulfilling the clinical criteria established by the International Gastric Cancer Linkage Consortium have constitutional alterations of the CDH1 gene." (PMID 33809393, 2021). "Next, drugging assays were performed on an isogenic cell line pair derived from gastric cancer cells in which CDH1 deletion was generated by CRISPR-Cas9: NCI-N87-WT and NCI-N87-CDH1−/−." (PMID 35008338, 2021). "Surprisingly, both CDH1+/+ and CDH1−/− cells derived from the NCI-N87 gastric cancer cell line exhibited similar sensitivity to chloroquine treatment, demonstrating the importance of genetic background to drug response." (PMID 35008266, 2021). "The PRC2 complex that establishes repressive H3K27me3 marks has been shown recruited on the Kruppel Like Factor 2 (KLF2) and CDH1 promoters in gastric cancer cells." (PMID 33803458, 2021). "CDH1 gastric cancers present as signet-ring cell adenocarcinomas (SRCCs) with abundant intracellular mucin, and readily metastasize before forming significant macroscopic primary lesions, accounting for their typical late stage at detection." (PMID 34073553, 2021). "Overall, these results illustrate the complex, but connected, relationships between the different HDAC classes and transcriptional patterns involving CDH1 in gastric cancer." (PMID 35008338, 2021). "Indeed, some of these age-related differences might be explained by age-related subtypes, such as the high prevalence of CDH1 mutation in invasive lobular breast carcinoma and GS stomach cancer, that are presented more often in older and younger patients, respectively." (PMID 33879792, 2021).
gastric cancer (continued). "In 2019, the international gastric cancer linkage consortium revised the clinical criteria and established guidelines for the genetic screening of CDH1 germline syndromes." (PMID 32560361, 2020). "· On combining the keywords which were relevant for the current study, CDH1 and Gastric Carcinoma showed 127 peer-reviewed pubmed articles." (PMID 33062523, 2020). "CDH1 is known as tumor suppressor and its down regulation in several cancers such as gastric cancer is reported." (PMID 31191840, 2019). "Bioinformatics analysis indicates that there is a strong correlation between the loss of CDH1 and an increased expression of AKT3 in gastric cancer." (PMID 31540244, 2019). "MiR-217 overexpression enhanced gastric cancer cells proliferation and reduced the exosomal level of CDH1, which can be delivered into the microenvironment." (PMID 31212809, 2019). "Although these differences are not always very strong, they are similar to the ones obtained with genes that are well known to be differently expressed between gastric cancer subgroups, such as E-cadherin (CDH1)." (PMID 31703394, 2019). "We have used next-generation sequencing, Sanger sequencing, and Multiplex Ligation-dependent Probe Amplification to examine germline CDH1 in an unselected series of 94 Māori gastric cancer patients and 200 healthy matched controls." (PMID 29589180, 2019). "We found that CDH1 is transcriptionally downregulated in 42.4% of IGCs, further confirming the importance of CDH1 downregulation in this gastric cancer histotype." (PMID 31509966, 2019). "To further investigate the relationship between the loss of CDH1 on AKT isoforms 1 and 3 in breast and gastric cancer cells, we measured the isoform protein expression in our cells." (PMID 31540244, 2019). "To explore the relationship between AKT isoform and CDH1 expression in gastric cancer, we performed an analysis of gene expression data from a stomach cancer database containing information from 415 tumours (TCGA, STAD cohort)." (PMID 31540244, 2019). "Due to the important role of CDH1 alterations in gastric cancer, the aim of this study was to analyze CDH1 somatic alterations (mutations, LOH and methylation) in Mexican patients with DGC and MGC." (PMID 30642281, 2019). "A few percent of all gastric cancers are defined as HDGC and 30–50% of patients meeting the clinical criteria for HDGC have germline CDH1 mutations." (PMID 31467357, 2019). "Driver genes in gastric cancer, such as CDH1 and FAT4, were present in area D2, and genes involved in cell adhesion were enriched." (PMID 31829249, 2019). "Aberrant splicing of CDH1 gene transcript (exon 8 or exon 11 skipped aberrant transcripts) was also reported in gastric carcinoma." (PMID 31781079, 2019). "CDH17 is a known gastric cancer marker while upregulation of CDH1 inhibits pancreatic cancer metastasis." (PMID 29515771, 2018). "Drug screening studies in isogenic CDH1−/−-mutant mammary epithelial MCF10A and c.1380delA CDH1-mutant gastric cancer cells show considerable overlap in sensitivity to PI3K, mTOR, or ALK/ROS-1 like tyrosine kinase inhibition." (PMID 29468433, 2018). "Liquid biopsies based on cell-free circulating DNA have been used to detect CDH1 promoter methylation in the plasma/serum of gastric cancer patients." (PMID 30568591, 2018). "Thus, activation of PI3K-mTOR signaling in CDH1-deficient gastric cancer cells might be the result of multiple signal transduction aberrations including lack of suppression of ligand-mediated EGFR activation or lack of negative feedback inhibition of the PI3K–Akt axis via reduced PTEN levels." (PMID 29468433, 2018).
gastric cancer (continued). "The same authors also found that overexpression of DNMT3A is responsible for methylating the CpG islands in the CDH1 promoter region, which lead to E-cadherin down regulation and increased malignancy of gastric cancer cells." (PMID 30376837, 2018). "The authors observed high correlation of promoter hypermethylation of CDH1 with gastric cancer, which shows that epigenetics and CDH1 are important to GC ethology." (PMID 29867026, 2018). "This is best exemplified for mutations in E-cadherin gene (CDH 1) which when homozygote, result in gastric carcinomas of diffuse type at an early age." (PMID 30567376, 2018). "In this study we explored the clinical relevance of breast and gastric cancer-associated polymorphisms in AXIN2 and CDH1 with NSCL ± P risk in the Brazilian population." (PMID 28376813, 2017). "Only in a little percentage of family affected by gastric cancer (4%) have large deletions of CDH1 gene been identified." (PMID 29094049, 2017). "We combined the differential pharmacological responses with gene expression profiles between c.del1380A CDH1 and a cohort of sporadic gastric cancer cells." (PMID 28460635, 2017). "We performed CDH1 gene expression analysis on fresh-frozen tissue samples from 32 patients with gastric cancer of the intestinal type." (PMID 27861150, 2017). "Metastatic hereditary diffuse gastric cancer c.1380delA CDH1 SB.mhdgc-1 cells harbor distinct transcriptomic profile compared to a cohort of sporadic gastric cancer cell lines." (PMID 28460635, 2017). "The presence of extracellular matrix adhesion molecules rescued impaired adhesion of c.1380delA CDH1 SB.mhdgc-1 cells, albeit significantly less compared to SB.msgc-1 sporadic gastric cancer cells." (PMID 28460635, 2017). "When measuring the ratio of adherent versus non-adherent cells at 2.5 and 5 h after seeding of cells, adhesion of c.1380delA CDH1 SB.mhdgc.-1 gastric cancer cells was substantially reduced compared to CDH1 wild type sporadic SB.msgc-1 cells." (PMID 28460635, 2017). "Next, we examined apoptosis levels upon treatment in c.1380delA CDH1 SB.mhdgc-1 and sporadic gastric cancer lines." (PMID 28460635, 2017). "C, Concomitant dysregulation of target genes and selective activity of MIPE compounds in c.1380delA CDH1 SB.mhdgc-1 versus SB.msgc-1 gastric cancer cells." (PMID 28460635, 2017). "CDH1 is one of the most important suppressor genes in gastric cancer; its inactivation increases tumour cells proliferation, invasion, and metastasis." (PMID 29094049, 2017). "B, LogAC50 distributions of compounds that show CRC −1.1, −1.2, −2.1, or −2.1 and logAC50 <−1 organized by enriched target class in c.1380delA CDH1 SB.mhdgc-1 versus SB.msgc-1 gastric cancer cells." (PMID 28460635, 2017). "We first aimed to validate the increased activity of the dual PI3K/mTOR and topoisomerase II inhibitors in hereditary c.1380delA CDH1 SB.mhdgc-1 gastric cancer cells in an extended panel of sporadic gastric cancer cell lines." (PMID 28460635, 2017). "Missense mutations at codon 400 in CDH1 and at codon 570 in CDH10 have been previously reported in gastric carcinoma (COSMIC IDs COSM1159626, COSM20771) and urinary tract carcinoma (COSM1311079), respectively." (PMID 29287594, 2017). "These CDH1 germline mutations (c.1849G > A; c.1023T > G) are thefirst described in association with HDGC and early onset gastric cancer from Brazilrevealed by a Next-Generation Sequencing platform." (PMID 27192129, 2016). "A study of CDH1 deletions in inherited gastric cancer identified two families with deletions that overlap the intervals prioritized in the present study." (PMID 27067391, 2016). "In gastric cancer, it has been demonstrated that hypermethylation of CDH1, which expresses the E-cadherin protein, is associated with DNMT1 overexpression by EBV infection." (PMID 26032781, 2015). "Greater CDH1 1054del83 transcripts were observed in gastric cancer (GC) cell lines than human gastric mucosal epithelial cell line GES-1." (PMID 26674321, 2015).